TEX11 (testis expressed 11)
Diseases named in the same sentence as TEX11 in open-access papers (continued):
Sharing a sentence is not in itself a finding about the gene and the disease.
Testicular atrophy (1 paper, 2024). Wasting (atrophy) of the testicle (the male gonad) manifested by a decrease in size and potentially by a loss of fertility. "In the same report, screening of a series of 289 azoospermic men revealed five other variants in the TEX11 open reading frame (three meiotic arrests, one mixed testicular atrophy, and one partial meiotic arrest)." (PMID 39231187, 2024). "The deletion of TEX11 exons 10 to 12 was first identified in two azoospermic patients: one with mixed testicular atrophy, and the other with meiotic arrest." (PMID 39231187, 2024).
tumor (1 paper, 2022). "We expect that our findings can be applied to the improvement of cisplatin-based chemotherapy for TGCT, particularly for TEX11-overexpressing tumor." (PMID 36319719, 2022). "It is also notable that PCNA protein levels were relatively decreased in the siTEX11-treated tumors compared with siControl-treated tumors, suggesting that TEX11 silencing may repress the tumor proliferative activity." (PMID 36319719, 2022). "We further evaluated whether TEX11-specific siRNA can reduce in vivo tumor growth of cisplatin-resistant TGCT cells using a TGCT-PDC-R-derived xenograft model of NOD/SCID mice treated with cisplatin." (PMID 36319719, 2022).
TEX11 also shares sentences with these, for which no sentence is quoted: cancer (2 papers); Zinc deficiency (2); adrenal hyperplasia (1); coronary atherosclerosis (1); hypogonadotropic hypogonadism (1); Intellectual disability (1); ischemic heart disease (1); Kallmann syndrome (1); lymph node metastases (1); oligospermia (1).